RNU4-49P (RNA, U4 small nuclear 49, pseudogene)
Gene: Small nuclear RNA gene on chromosome 2 (48,340,687 to 48,340,826, reverse strand). Ensembl gene ENSG00000251889.
Homologues: Orthologues: chimpanzee U4 (99% identical), macaque U4 (95% identical), mouse Gm22005 (81% identical). Paralogues in human: RNU4-10P (84% identical), RNU4-36P (84% identical), RNU4-81P (82% identical), RNU4-32P (79% identical), RNU4-90P (79% identical), RNU4-46P (78% identical), RNU4-50P (78% identical), RNU4-17P (76% identical), RNU4-51P (76% identical), RNU4-52P (74% identical), RNU4-15P (73% identical), RNU4-83P (73% identical), and 81 more.